MGMT (O-6-methylguanine-DNA methyltransferase)
Diseases named in the same sentence as MGMT in open-access papers (continued):
Sharing a sentence is not in itself a finding about the gene and the disease.
glioblastoma (continued). "In glioblastoma patients undergoing radiotherapy as the sole post-resection treatment, the correlation between MGMT promoter methylation and enhanced response to radiotherapy was evident." (PMID 39055560, 2024). "Alarmingly, individuals with glioblastoma from lower socioeconomic backgrounds are less likely to undergo O6-Methylguanine-DNA-methyltransferase (MGMT) testing." (PMID 38553633, 2024). "Patients with MGMT-promoter-methylated glioblastoma typically have a better response to alkylating agent chemotherapy and have a longer overall survival compared to those with an unmethylated MGMT promoter." (PMID 38167551, 2024). "In analogy to SL tumors, MGMT promotor methylation is a significant prognostic factor of therapeutic response in ML glioblastoma." (PMID 39560695, 2024). "Levetiracetam (Lev), an antiepileptic drug (AED), enhances alkylating chemotherapy sensitivity in glioblastoma (GB) by inhibiting MGMT expression." (PMID 39653818, 2024). "Our weakly supervised prediction model based on H&E-stained histopathological slides proves to be an effective approach for predicting the MGMT promoter methylation status in glioblastoma." (PMID 38385046, 2024). "The methylation status of the O6-methylguanine DNA methyltransferase (MGMT) promoter region is a critical predictor of response to alkylating agents in glioblastoma." (PMID 38357209, 2024). "An example is a study that used conventional MRI in order to anticipate the MGMT promoter methylation status in patients with glioblastoma." (PMID 38827949, 2024). "Different mechanisms of chemoresistance exist in glioblastoma, such as the activation of methylguanine methyltransferase (MGMT), increased activity of ATP-binding transporters, tumor heterogeneity, the immunosuppressive microenvironment, and GSCs." (PMID 38794149, 2024). "The methylation of the MGMT promoter was apparent in approximately 50% of newly diagnosed glioblastomas in a few studies as well as this." (PMID 39767640, 2024). "Methylation of the MGMT promoter, which predicts the response to temozolomide, is a well-established prognostic marker for glioblastoma." (PMID 38454929, 2024). "In this retrospective analysis of a multicenter, open-label, phase-3 randomized clinical trial in patients with MGMT promoter-methylated glioblastoma treated with cilengitide, we reviewed MRI data from 545 patients according to the modified RANO criteria." (PMID 38219019, 2024). "This study is the first to implement the Transformer algorithm in MGMT research, opening new avenues for molecular studies of glioblastoma." (PMID 39716317, 2024). "In this study, based on the TCGA database and H&E-stained Whole slide images (WSI) of Beijing Tiantan Hospital, we constructed a weakly supervised prediction model of MGMT promoter methylation status in glioblastoma by using two Transformer structure models." (PMID 38385046, 2024). "Our investigation employed two neural networks with transformer-like architectures to predict the MGMT promoter methylation status in glioblastoma." (PMID 38385046, 2024). "PLOD3 was closely related to patients' age, glioblastoma grade, IDH mutation, 1p/19q deletion, MGMT methylation, and survival time." (PMID 39431006, 2024). "Although differences in the proportion of MGMT promoter methylation between male and female and female with glioblastoma have been proposed, it appears that the difference is not statistically significant." (PMID 38243318, 2024). "MGMT promoter methylation status: real-time quantitative methylation-specific PCR is performed to determine the status of DNA methylation in 8 FFPE glioblastomas (6 partial resection FFPE and 2 biopsy FFPE)." (PMID 40093343, 2024). "Histopathological analysis of the tumor sample confirmed a high-grade glioma consistent with glioblastoma, characterized as IDH-wild type, MGMT-unmethylated, and BRAF V600E-mutated." (PMID 39759633, 2024).
glioblastoma (continued). "MGMT promoter methylation plays a crucial dual role in managing glioblastoma, both as a predictor of patient sensitivity to TMZ and as a marker of overall prognosis." (PMID 39767571, 2024). "Recent studies have highlighted the significance of lomustine, an alkylating agent, in the treatment of newly diagnosed MGMT methylated glioblastoma, despite previous assertions of limited data supporting its definitive interaction with MGMT." (PMID 39055560, 2024). "Glioblastomas exhibit higher methylation of O6-methylguanine-DNA methyltransferase (MGMT), which results in impairment of DNA repair with the use of alkylating agents." (PMID 38391759, 2024). "Response to chemotherapy with alkylating substances is significantly better in IDH wt glioblastoma when the MGMT promoter is methylated." (PMID 38326661, 2024). "Therapeutic strategies in glioblastoma have focused on blocking MGMT activation, either through epigenetic agents that modulate the methylated state of the MGMT gene promoter or through direct inhibition of the MGMT protein." (PMID 39518074, 2024). "PDCD10 knockdown upregulated MGMT, a key enzyme mediating chemo-resistance in glioblastoma, accompanied by increased expression of DNA mismatch repair genes, and enabled tumor cells to evade TMZ-induced cell-cycle arrest." (PMID 39273014, 2024). "PTBP1 was closely related to patients' age, glioblastoma grade, IDH mutation, 1p/19q deletion, MGMT methylation, and survival time." (PMID 39431006, 2024). "To summarize, we investigated relationships between MGMT methylation status and glioblastoma location through multiple approaches, including voxel-wise analyses." (PMID 39713243, 2024). "The efficacy of these chemotherapy regimens depends on the methylation of a specific gene promoter known as MGMT, which is the main prognosis factor for glioblastoma." (PMID 37190181, 2023). "This seems to be the case in particular in glioblastomas, since about 20% of tumors lack MGMT enzyme activity and about 40% are methylated in the promoter, as shown by methylation-specific PCR assays." (PMID 38068493, 2023). "Since the DNA methylation status of the MGMT promoter has an impact on MGMT expression, it serves as biomarker for predicting the response to temozolomide and prognosis of glioblastoma." (PMID 38136323, 2023). "In our study, a single-centre retrospective study, we explore the impact of MGMT promoter methylation in patients with glioblastoma who were operated upon with 5-ALA." (PMID 37373988, 2023). "In agreement with our results, valganciclovir possessed a positive effect on glioblastoma tumors with an unmethylated or methylated MGMT promoter gene, potentially through its antiproliferative effect." (PMID 37147437, 2023). "MGMT promoter methylation status has emerged as a prognostic and predictive biomarker for patients with newly diagnosed glioblastoma (GBM)." (PMID 37371109, 2023). "In the randomized phase III trial CeTeG/NOA-09, temozolomide (TMZ)/lomustine (CCNU) combination therapy was superior to TMZ in newly diagnosed MGMT methylated glioblastoma, albeit reporting more frequent hematotoxicity." (PMID 36609807, 2023). "The MGMT promoter methylation LASSO regression (predicting glioblastomas with methylated MGMT promoters compared to controls) yielded 91% sensitivity and 73% specificity for the test dataset, using 17 of 569 genes." (PMID 37568598, 2023). "Here, we aim to replicate these findings and analyze the potential impact of glioblastoma gene expression subgroups on the benefit from first-line treatment with bevacizumab in an independent study cohort of MGMT-unmethylated glioblastoma." (PMID 37787906, 2023). "Few studies in in literature have authenticated that methylation of MGMT promoter sequence serves as a powerful prognostic and predictive tool for longer overall survival and progression free survival in patients with glioblastoma 1,13,21." (PMID 39760063, 2023).
glioblastoma (continued). "Advancements in specific drug discoveries for targeting MGMT promoters, occurring in glioblastoma, can lead to better prognosis and OS in several cases with MGMT unmethylated tumor cells, i.e. in primary glioblastoma patients." (PMID 37937301, 2023). "Molecular mechanisms underlying TMZ resistance have been previously investigated, involving DNA repair systems like O-6-methylguanine-DNA methyltransferase (MGMT), metabolic reprogramming, and glioblastoma stem-like cells (GSCs)." (PMID 37759808, 2023). "Because patients with methylated MGMT gene have survival advantage, synthetic inhibitors of MGMT were tested in glioblastoma patients (NCT00613093)." (PMID 37974198, 2023). "In the TCGA set, patients with higher risk score tend to be older than 40 years, to have higher WHO grade, unmethylated MGMT promoter, glioblastoma, non‐codeletion of 1p/19q and wild type IDH1 (all p < 0.001)." (PMID 36856182, 2023). "IL-6 is a cytokine that is known to trigger JAK-STAT3 signaling in glioblastoma, gliomagenesis, MGMT methylation, and is correlated with tumor grade and overall patient survival." (PMID 37752585, 2023). "In the CeTeG/NOA-09 trial, 650 patients were initially screened, among whom, 141 patients aged 18-70 years with MGMT-methylated glioblastoma were selected for enrollment and randomly assigned to one of two treatment groups." (PMID 37881322, 2023). "In the randomized CeTeG/NOA-09 trial, combined lomustine (CCNU)/TMZ was superior to TMZ therapy regarding OS in newly diagnosed patients with MGMT-methylated glioblastoma." (PMID 37728779, 2023). "We selected IDH-wildtype glioblastomas from patients who either survived longer than 3 years or died within the first year after initial diagnosis and compared the MGMT methylation pattern of these tumors." (PMID 37641156, 2023). "Previous studies have investigated the performance of other methods to assess MGMT status, especially in the glioblastoma setting." (PMID 36826067, 2023). "Only single studies have systematically investigated the methylation status of larger areas of MGMT in glioblastoma specimens." (PMID 37641156, 2023). "Conflicting, or at least controversial, data about the importance of MGMT methylation, compared to what happens in glioblastomas, are also in other oncological settings, such as in pancreatic neuroendocrine neoplasms, strongly related to their heterogeneity." (PMID 37371106, 2023). "A major prognosis factor for glioblastoma patients is the methylation status of the DNA repair enzyme MGMT." (PMID 37190181, 2023). "The relationship between MGMT methylation and increased overall survival, possibly due to response to temozolomide treatment, is of major interest to clinicians dealing with glioblastoma patients." (PMID 37641156, 2023). "In a study on glioblastomas, in which we determined MGMT activity and promoter methylation in the same specimens, about 20% of the samples were completely lacking MGMT, whereas 40% were methylation positive." (PMID 38068493, 2023). "A recent report showed that TMZ induced the expression of O6-methylguanine DNA-methyltransferase (MGMT), a DNA repair enzyme that favors glioblastoma cell resistance, and MnSOD, an antioxidant gene, in the glioblastoma cell lines SHG-44 and U251." (PMID 37174661, 2023). "Currently, the methylation status of the MGMT promoter or MGMT activity is used as a prognostic predictor factor for the outcome of glioblastoma patients undergoing chemotherapy based on temozolomide." (PMID 37371106, 2023). "O6-methylguanine DNA methyltransferase (MGMT) is an enzyme that confers glioblastoma with chemotherapeutic resistance." (PMID 37509281, 2023). "The vast majority of the literature that assesses the impact of MGMT promoter methylation precedes the widespread use of 5-Aminolevulinic Acid (5-ALA) in glioblastoma surgery." (PMID 37373988, 2023).
glioblastoma (continued). "The outcome of glioblastoma patients treated with temozolomide is therefore inversely related to the level of expression of enzyme MGMT." (PMID 39760063, 2023). "With this technology, we develop an assay to analyze the methylation status of a region of the MGMT promoter used in treatment selection and prognosis of glioblastoma patients." (PMID 37620381, 2023). "In this study, we propose a novel two-stage MGMT Promoter Methylation Prediction (MGMT-PMP) system that extracts latent features fused with radiomic features predicting the genetic subtype of glioblastoma." (PMID 36841898, 2023). "Our retrospective study confirms differences in age and MGMT methylation pattern between long-term and short-term survivors of glioblastoma." (PMID 37641156, 2023). "The MGMT gene is mostly obtained as unmethylated in primary glioblastoma brain tumors, while in secondary glioblastoma brain tumors, the MGMT occurs as a methylated one." (PMID 37937301, 2023). "The highest classification performance is (96.84 ± 0.09)%, (96.08 ± 0.10)%, and (97.44 ± 0.14)% as accuracy, sensitivity, and specificity respectively to detect MGMT methylation status for patients suffering from glioblastoma." (PMID 36841898, 2023). "Scalp sparing radiation with concurrent temozolomide and TTF is well tolerated by patients, furthermore, a better response for glioblastoma patients with methylated O6-methylguanine DNA methyltransferase (MGMT) promoter has been observed." (PMID 36765840, 2023). "Two articles used radiomics approaches and machine-learning techniques to predict the molecular markers (IDH1 and MGMT) and prognoses of glioblastomas and gliomas." (PMID 37568660, 2023). "The median survival for patients with glioblastoma treated according to current standard treatment has moderately but significantly increased, with MGMT promoter hypermethylation as the strongest predictor for survival." (PMID 37711136, 2023). "A new publishment reported that the combination of TTFields and TMZ plus CCNU can provide additional survival benefits for newly diagnosed MGMT promoter methylated glioblastoma patients." (PMID 36987739, 2023). "The relapse pattern of glioblastomas can be moderately changed by dose escalation of radiotherapy, by temozolomide for MGMT promoter hypermethylated glioblastomas, or addition of TT-Fields towards more marginal or out-field recurrences." (PMID 37296942, 2023). "Epigenetic inhibition of the O6-methylguanine-DNA-methyltransferase (MGMT) gene has emerged as a clinically relevant prognostic marker in glioblastoma (GBM)." (PMID 37899778, 2023). "MGMT has been the biomarker with the most meaningful influence in clinical decision making for resilient glioblastomas since its discovery." (PMID 37754483, 2023). "We therefore maintain that this region needs additional scrutiny for further refinement of the MGMT methylation status of glioblastomas." (PMID 37641156, 2023). "In glioblastoma, IHC is often used to analyze MGMT protein expression, and MGMT levels are assessed by the percentage of MGMT-positive cells in the nucleus." (PMID 37161026, 2023). "This article is related to the prediction of MGMT promoter methylation status, a genetic characteristic of glioblastoma, using baseline MRI scans done before and while preparing for a surgical operation." (PMID 36841898, 2023). "Several clinical trials have demonstrated the prognostic significance of the methylation status of the MGMT promoter in glioblastoma patients." (PMID 37894355, 2023). "In the randomized CeTeG/NOA-09 trial, lomustine/temozolomide (CCNU/TMZ) was superior to TMZ therapy regarding overall survival (OS) in MGMT promotor-methylated glioblastoma." (PMID 37728779, 2023).
glioblastoma (continued). "The confirmation of the importance of the MGMT methylation status can be seen as an important step in the improvement of the patient selection of iPDT for de novo glioblastomas." (PMID 37174068, 2023). "In human glioblastoma cells, however, we were unable to detect any induction at doses in the therapeutic range, but we observed the upregulation of MGMT by glucocorticoids, which is in line with the presence of GREs in the MGMT promoter." (PMID 38068493, 2023). "Epigenetic silencing of the DNA repair gene MGMT has proven utility as a positive predictor of the therapeutic efficacy of the alklyating drug temozolomide (TMZ) in tumours such as glioblastoma multiforme." (PMID 36198483, 2023). "We found two genes, PSMC1P10 and AL132708.1, specific to patients with IDH1-wt and MGMT-methylated glioblastoma." (PMID 37568598, 2023). "The combination of lomustine and temozolomide has been proven to be beneficial over temozolomide in patients with MGMT promotor methylated glioblastoma in the NOA-09/CETEG trial and is currently evaluated in patients with 1p/19q codeletion." (PMID 36566461, 2023). "TMZ would have been a breakthrough in the treatment of glioblastoma, nonetheless, the MGMT (O-6-methylguanine DNA methyltransferase) gene in tumors is responsible for the repair of DNA, and hence nullifies the effect of TMZ." (PMID 37937301, 2023). "In the absence of a clinical trial setting, we propose the administration of temozolomide in conjunction with RT for most patients diagnosed with MGMT-unmethylated glioblastoma." (PMID 37881322, 2023). "MGMT promoter methylated glioblastoma tends to reveal limited peritumoral edema, high ADC values, and low CBV." (PMID 37754483, 2023). "We investigated prognostic parameters and outcome in a retrospective cohort of patients with newly diagnosed glioblastoma aged 80 years or older and stratified the cohort according to the MGMT promoter methylation status as proposed by previous publications." (PMID 37289281, 2023). "Deep learning feature extraction with radiogenomic features, fusing imaging phenotypes and molecular structure, using rejection algorithm has been found to perform outclass capable of detecting MGMT methylation status of glioblastoma patients." (PMID 36841898, 2023). "Research of this nature will assist to further characterizing the inherent qualities of the relationship between MGMT promoter methylation and survival in glioblastoma." (PMID 37899778, 2023). "It is recommended that patients who have recently been diagnosed with MGMT-methylated glioblastoma and are ≤ 70 years old be treated with concurrent temozolomide along with RT, followed by monthly adjuvant temozolomide." (PMID 37881322, 2023). "Temozolomide is an oral alkylating agent approved for patients with glioblastoma, and the efficacy of the drug in this disease is related to a validated predictive biomarker; the O6-methylguanine-DNA methyltransferase (MGMT) promoter methylation." (PMID 37958363, 2023). "A previous study presented the findings of a phase II clinical trial involving 182 patients who were diagnosed with newly acquired glioblastoma and exhibited unmethylated MGMT." (PMID 37881322, 2023). "An example of the predictive value of the DNA methylation of the MGMT gene promoter in response to temozolomide therapy in glioblastoma shows that the comprehensive characterization of DNA methylation patterns is important in both normal and cancer genomes." (PMID 38139172, 2023). "Our data confirm previously published prognostic factors in IDH-wildtype glioblastoma patients, including age and temozolomide treatment as well as the global MGMT methylation status." (PMID 37641156, 2023). "Two genes, MTND6P33 and RNU1-2, were specific to glioblastoma patients with TERT promoter mutations and MGMT methylation." (PMID 37568598, 2023).